CXCL12 (C-X-C motif chemokine ligand 12)
Diseases named in the same sentence as CXCL12 in open-access papers (continued):
Sharing a sentence is not in itself a finding about the gene and the disease.
breast carcinoma (continued). "However, more in-depth studies based on other tumor-related genetic polymorphisms of CXCL12, and their associations with breast cancer susceptibility are not yet fully understood." (PMID 39703847, 2024). "Moreover, CCL2 SNPs were more likely to be associated with PR-positive breast cancer, while CXCL12 SNPs were associated with three main subtypes of breast cancer." (PMID 39703847, 2024). "SNPs in the CCL2 gene were mainly associated with PR-positive breast cancer, whereas rs1144471 in CXCL12 was associated with ER-negative (OR=0.43, 95% CI=0.23-0.84), PR-negative (OR=0.38, 95% CI=0.19-0.74), and HER-2-positive (OR=1.27, 95% CI=1.03-1.56) breast cancer." (PMID 39703847, 2024). "Furthermore, in various tumors, including lung cancer, breast cancer, and colorectal cancer, the activation of the CXCL12/CXCR4/ACKR3 signaling axis has been associated with STAT3 pathway activation." (PMID 38920657, 2024). "Association of CCL2 and CXCL12 gene SNPs with Breast Cancer subtypes." (PMID 39703847, 2024). "However,rs3740085 in CXCL12 showed a significant association with an increased risk of breast cancer (additive model: OR =1.15, 95% CI=1.01-1.32, dominant model: OR =1.18, 95% CI=1.01-1.37)." (PMID 39703847, 2024). "In this study, we examined whether eight single nucleotide polymorphisms (SNPs) of CCL2 and CXCL12 influenced the susceptibility to breast cancer and analyzed their relationships with different subtypes of breast cancer." (PMID 39703847, 2024). "Here, we hypothesize that the CXCL12/CXCR4/mTOR/HIF-1α axis in DPP-4-deficient cells plays a key role in the activation of autophagy in breast cancer cells to promote survival." (PMID 37760498, 2023). "In addition, multiple meta-analyses showed that CXCL12 expression improved the prognosis of breast cancer patients, which was consistent with our results that CXCL12 had a reverse causal association with breast cancer." (PMID 38075694, 2023). "In a meta-analysis on cancer prognosis, high CXCL12 expression was associated with reduced absolute survival in patients with esophagogastric, pancreatic or lung cancer whereas the opposite was true in breast cancer patients." (PMID 37966614, 2023). "High expression of CXCL12 was linked with a prolonged survival in breast cancer." (PMID 37564657, 2023). "It has been described that cancer associated with metastasis disease like breast cancer may rely on downregulation of CXCL12 to advance to ectopic sources, as they may be more susceptible to chemoattraction when turned off." (PMID 37966614, 2023). "The CAF-driven CXCR4/CXCL12 axis may also stimulate the accumulation of protumorigenic lipid associated macrophages which supports an immunosuppressive microenvironment in breast cancer." (PMID 36588678, 2022). "In addition, polymorphisms of CXCL12 were considered as factors affecting the susceptibility and prognosis to breast cancer." (PMID 35079936, 2022). "However, our results were inconsistent with the previous meta-analysis, which indicated that CXCL12 rs1801157 polymorphism increased the risk of breast cancer in allelic genetic, homozygote, heterozygote, recessive genetic and dominant genetic models." (PMID 35079936, 2022). "Thus, in this study, we aimed to figure out the association between three CXCL12 polymorphisms (rs1801157, rs2297630, and rs2839693) and breast cancer susceptibility in Chinese population." (PMID 35079936, 2022). "Elevated CXCL12 expression was also significantly related with the reduced absolute survival in patients with oesophagogastric, pancreatic, or lung cancer, but associated with the increased absolute survival in patients with breast cancer." (PMID 35079936, 2022). "CXCL12 and its receptor enables a permissive microenvironment for angiogenesis, since it has been demonstrated that cancer associated fibroblast inoculated in breast cancer caused enhanced tumor growth and development as compared to normal fibroblasts." (PMID 34445691, 2021).
breast carcinoma (continued). "CXCL12 levels has been shown to have prognostic significance in cancer, with high levels associated with adverse outcome in esophagogastric, pancreatic, and lung cancer; and, conversely, associated with enhanced survival in breast cancer." (PMID 34842843, 2021). "Notably, the CXCL12/CXCR7/CXCR4 axis plays an important role in breast cancer growth and metastasis, but only CXCL12 has been associated with disparate expression." (PMID 32824813, 2020). "Notably, BCSCs have high CXCR4 expression and are defined as a pro-metastatic subpopulation, whereas the expression of CXCL12 defines regions with a higher risk of causing metastasis for breast cancer invasion." (PMID 32751846, 2020). "Similarly, the expression of CXCL12 is associated with pathological features and clinical outcomes in human breast cancer." (PMID 33363463, 2020). "CXCL12 expressed by CAFs causes EMT in breast cancer and human tongue squamous cell carcinoma." (PMID 33414786, 2020). "Elevated expression of CXCL12 and other stem cell factors in primary human breast cancer-associated fibroblasts indicates that certain fibroblast populations support tumor cell stemness and thereby promote breast cancer growth." (PMID 29632733, 2018). "In addition, CXCL12 hypermethylation has been shown to be associated with lymph node metastasis development and higher proliferation rates of breast cancer cells." (PMID 28272462, 2017). "Due to a known metastatic function of chemokine, CXCL12 variant is considered as a risk factor and has been previously reported in association with multiple cancers including myeloma, colorectal, cervical, basal cell and breast carcinoma." (PMID 28929029, 2017). "Through RNA-Seq and protein analyses, we found that cancer-associated fibroblasts derived from human breast cancer brain metastasis express significantly higher levels of chemokines CXCL12 and CXCL16 than fibroblasts from primary breast tumors or normal breast." (PMID 28649646, 2017). "CXCR4 is a receptor for chemokine CXCL12 and has recently been linked to breast cancer metastasis." (PMID 26993780, 2016). "In fact, CXCL12 expression was associated with disease-free and overall survival in a highly significant manner in two independent microarray gene expression datasets as well as in 100 breast cancer cases, analysed by IHC." (PMID 26161302, 2015). "Furthermore, the down-regulation of CXCL12 expression by promoter hypermethylation has been associated with increased metastatic potential in mammary carcinoma cells by the loss of autocrine and paracrine CXCL12 retention at the primary tumor site." (PMID 24906407, 2014). "The analysis stratified by cancer type found that CXCL12 G801A polymorphism may increase the risk of breast cancer, lung cancer, and “other” cancers." (PMID 25268356, 2014). "Moreover, high levels of CXCL12 expressed by cancer cells and tumor-associated stromal cells directly stimulate the proliferation and invasiveness of breast cancer cells in the autocrine and paracrine manners." (PMID 25471741, 2014). "In addition, there was upregulated expression of two genes that have previously been shown to be highly associated with tumor-associated fibroblasts in breast cancer (CXCL12 and CLIC4) and upregulation of the COX2 gene." (PMID 15987422, 2005). "However, the association between SNPs in the CCL2 and CXCL12 genes and the susceptibility to breast cancer remains unclear." (PMID 39703847, 2024). "Additionally, we found a strong association between plasma CXCL12 and breast cancer." (PMID 39703847, 2024). "Genetic polymorphisms of CCL2 and CXCL12 may influence the binding of transcription factors to these genes, affecting promoter activity and gene transcription, and therefore they may have varying impacts on developing breast cancer." (PMID 39703847, 2024).
breast carcinoma (continued). "Therefore, we investigated whether the combination of TMB and the CXCL12-related risk score could jointly stratify breast cancer patients into groups with conspicuously distinct prognoses." (PMID 37564657, 2023). "Finally, environmental exposure and ethnic differences may affect the susceptibility and clinical indicators of breast cancer, so the correlation between CXCL12 and other factors remains to be studied." (PMID 35079936, 2022). "The CXCL12 G801A polymorphism may be essential to increasing the production of a CXCL12 protein that has been shown to be associated with an increased risk of various kinds of cancers, such as breast cancer, lung cancer and lymphoma." (PMID 25268356, 2014). "A recent report proposed that fibroblasts influenced by osteopontin produced by breast cancer cells secrete CXCL12, driving cancer cell epithelial‐mesenchymal‐transition and neoangiogenesis." (PMID 39887653, 2025). "Breast cancer cells that exhibit an elevated expression of CXCR4 have a greater tendency to be attracted by CXCL12, which is secreted by osteoblasts and plays a role in attracting osteogenic precursors to bone marrow." (PMID 39980332, 2025). "The CXCL12/CXCR4 signaling axis is regulated by the tumor suppressor gene Il-24 and is strongly associated with breast cancer." (PMID 40076586, 2025). "For example, the CXCR4 inhibitor AMD3100 can mobilize HSCs, and inhibition of CXCR4/ CXCL12 signaling has been shown to be useful as an adjuvant in the treatment of hematological malignancies (e.g., leukemia) and solid tumors (e.g., breast cancer)." (PMID 40979214, 2025). "The chemokine receptor CXCR4 and its ligand CXCL12 play a significant role in breast cancer cell colonization in bone." (PMID 39980332, 2025). "bone-derived CXCL12 preferentially recruits breast cancer cells with high CXCR4 expression to bone metastasis sites." (PMID 40510151, 2025). "Dąbrowska examined the expression of CXCL12 and CXCR4 in 100 breast cancer patients, revealing that analyzing the expression levels of CXCL12/CXCR4 can enhance the accuracy of breast cancer diagnosis." (PMID 40607416, 2025). "The α-SMA+ CAFs can promote the generation and proliferation of CD44+CD24− breast cancer stem cells by secreting CXCL12 that activates CXCR4 on cancer cells." (PMID 39780187, 2025). "Other studies investigating applications of heparin on breast cancer and related chemokines found that heparin dodecasaccharides represent the minimal chain length to bind and inhibit CXCL12 effectively." (PMID 40723905, 2025). "A previous study of human mammary carcinoma-derived CAFs demonstrated that autocrine TGF-β signaling can upregulate CXCL12 expression through Smad2/3 activation." (PMID 40849508, 2025). "In fact, it has been shown that some chemokine, including CXCL12, are able to regulate breast cancer stem cell behavior." (PMID 39859358, 2025). "In primary breast cancer samples, there were higher levels of iCAFs, which were identified by high expression of cytokines such as CXCL12, CXCL14, and IL686." (PMID 40858590, 2025). "In vivo, suppressing CXCL12/CXCR4 interactions drastically decreased breast cancer cell metastasis to the surrounding lymph nodes and lungs." (PMID 40548301, 2025). "Chemokine receptor 4 (CXCR4), the receptor of chemokine CXCL12/SDF-1 (stromal cell-derived factor-1) has been identified as a potential target for breast cancer imaging and therapy." (PMID 40075611, 2025). "In breast cancer, iCAFs promote T‐cell exclusion by secreting CXCL12, which binds to CXCR4 on T cells." (PMID 41164803, 2025). "For instance, prostate and breast cancers frequently metastasize to bone, where they are drawn by chemoattractants like osteopontin and CXCL12, as well as the acidic pH, high calcium concentration, and availability of growth-promoting factors." (PMID 40871003, 2025).
breast carcinoma (continued). "CXCL12 binds CXCR4 to direct metastatic homing of breast cancer cells to bone marrow, lungs, and liver; high CXCL12/CXCR4 axis activity is a hallmark of bone-tropic metastases." (PMID 41007766, 2025). "This aligns with recent work linking RECQL4 to CXCL12 secretion in osteosarcoma but provides the first evidence of its immunomodulatory function in breast cancer." (PMID 41472745, 2025). "In breast cancer, iCAFs recruit myeloid cells in a CXCL12-dependent manner and enhance MMP activity, ultimately leading to increased tumour invasion." (PMID 39780187, 2025). "CXCL12 have crucial role in breast cancer progression by promoting invasion, angiogenesis and immune system modulation." (PMID 40297849, 2025). "This idea is further supported as the disruption of the CXCL12/CXCR4 axis has been shown to impair breast cancer metastasis in preclinical models." (PMID 40871003, 2025). "In CXCR4-positive cancers, such as breast cancer, the CXCL12/CXCR4 axis drives metastasis to organs rich in CXCL12, including the lungs, bone marrow, and lymph nodes." (PMID 40282969, 2025). "Male sex hormones, including testosterone, have also been reported to influence CXCL12 production and correlation between AR and CXCL12 expression was observed in breast cancer tissue." (PMID 40589738, 2025). "Cancer-associated fibroblasts (CAFs) also contribute to the network by promoting TAM recruitment through the CXCL12/CXCR4 axis in breast cancer (BC) and the IL-8/CXCR2 axis in colorectal cancer (CRC)." (PMID 41417432, 2025). "Of 321 formalin-fixed paraffin-embedded primary tumor tissue samples of patients with early breast cancer treated with chemotherapy, mRNA expressions of CXCL12, CXCL13, and CXCR5 were studied." (PMID 39001456, 2024). "Perivascular cells highly expressing CXCL12 in vascular microhabitats in bone marrow sinuses can keep breast cancer cells dormant in the vasculature through CXCL-12/CXCR4 interaction." (PMID 38464516, 2024). "Immunohistochemical analysis of bone marrow from breast cancer patients showed that dormant breast cancer cells preferentially localize in CXCL12-rich vascular regions." (PMID 38464516, 2024). "In breast cancer cells, AQP3 is associated with the induction of CXCL12/CXCR4-dependent cell migration, a critical process in breast cancer progression and metastasis." (PMID 39125952, 2024). "The exosome-derived lncRNA NEAT1 upregulated CXCL12 expression through competitively binding to miR-133b, promoted breast cancer cell migration and growth, and induced paclitaxel resistance in breast cancer cells." (PMID 38691224, 2024). "Our results showing that women with breast cancer had higher plasma levels of CXCL12, compared to healthy individuals, was confirmed in another population-based study." (PMID 39703847, 2024). "In breast cancer, the CXCL12/CXCR4/ACKR3 axis promoted breast cancer metastasis through the activation of the STAT3 pathway." (PMID 38920657, 2024). "These pseudopods enable the guided migration and invasion of breast cancer cells towards organs expressing its ligand, chemokines such as CXCL12, thereby facilitating breast cancer metastasis." (PMID 39769501, 2024). "Bone, lung, liver, and lymph node organs express high levels of CXCL12, which makes them preferred locations for malignant breast cancer cells to metastasize." (PMID 38360737, 2024). "In a variety of tumor cells, including gastric cancer, glioblastoma, and breast cancer, the activation of the CXCL12/CXCR4 axis has been observed to stimulate the SRC, ERK, and STAT3 pathways." (PMID 38920657, 2024). "In this study, we investigated the potential correlation between breast cancer susceptibility and eight specific SNPs within both the CCL2 and CXCL12 genes among the Chinese population." (PMID 39703847, 2024).
breast carcinoma (continued). "This case-control study emphasized the importance of having sufficient sample sizes to achieve a thorough assessment of the relationship between the CCL2, and CXCL12 SNPs and breast cancer." (PMID 39703847, 2024). "Chemokines like CXCL12 and E-selectin are abundantly present in the bone microenvironment, attracting breast cancer cells to the perivascular niche to faciltate mesenchymal-to-epithelial transition(MET), stemness and survival." (PMID 39605887, 2024). "Recent research has identified CAF-mediated CXCL12 expression as a defining characteristic of the “CAF-S1” immunosuppressive subtype of breast cancer myofibroblastic CAF (myCAF)." (PMID 39187523, 2024). "On the other hand, a TG2–dependent covalent CXCL12–keratin-19 (KRT19) heterodimer was described in breast cancer cells." (PMID 39544364, 2024). "CAFs in breast cancer with an immunosuppressive phenotype secrete CXCL12 that in turn recruits CD4+ T cells to the TME and are then polarized to regulatory T cells (Treg) by interacting with CAFs." (PMID 39310770, 2024). "Prior studies have highlighted the roles of TGF-β and SDF-1/CXCL12 in the differentiation of fibroblasts into CAFs and the promotion of a tumor-enhancing phenotype in breast cancer cells." (PMID 39195225, 2024). "Consistently, high expression of CCL2 or CXCL12 has been observed in patients with advanced (metastatic) breast cancer." (PMID 37307835, 2024). "After treatment with CA4P in murine breast cancer models, tumors significantly increased their levels of chemokine CXCL12 and repopulated the infiltration of proangiogenic TEMs." (PMID 38787372, 2024). "Chemokine receptor 4 (CXCR4) is highly expressed by breast cancer tissues, and its ligand, chemokine ligand 12 (CXCL12), is mainly in the lymph nodes." (PMID 39605887, 2024). "Summarily, the combined sample-paired snRNA-seq and spatial transcriptome analysis uncovers the expression pattern of CXCL12 in the breast cancer tissue." (PMID 37564657, 2023). "Considering different expression levels of CXCL12 among diverse molecular subtypes of breast cancer, we conducted the survival analyses among every subtype." (PMID 37564657, 2023). "To explore the complex role of CXCL12 in breast cancer, we first evaluated the expression levels of CXCL12 in breast cancer tissues and non-tumor tissues in the TCGA breast cancer cohort." (PMID 37564657, 2023). "Nevertheless, in breast cancer, high expression of CXCL12 is related to a prolonged OS and DFS, probably owing to decreased metastasis of breast malignant cells as found in the preclinical models." (PMID 37564657, 2023). "Immunohistochemistry analysis of the tissue microarray was performed to evaluate the correlation between CXCL12 expression levels and breast cancer patient outcomes." (PMID 37564657, 2023). "For example, CXCL4 when combined with CXCL12 forms a CXC-type heterodimer that is inhibitory for migration of breast cancer cells." (PMID 37446102, 2023). "A dipeptidyl peptidase (DPP)-4 inhibitor accelerated breast cancer metastasis by inducing EMT through CXCL12/CXCR4/mTOR axis, while metformin countered the harmful effect of DPP-4 inhibitor on breast cancer metastasis." (PMID 37497001, 2023). "CXCL12 can increase the migration and proliferation of stromal cells in breast cancer by recruiting CXCR4, which is related to breast cancer cell lymph node metastasis." (PMID 36755259, 2023). "Taken together, we built and validated a novel CXCL12-related prognostic signature for predicting the outcomes of breast cancers." (PMID 37564657, 2023). "It has been well established that the neutrophil chemokine axis CXCR4/CXCL12 is crucial in recruiting neutrophils to the pre‐metastatic niche such as in breast cancer, and CXCL12 is upregulated in several different metastatic sites as reviewed by Chen and Yu." (PMID 38062888, 2023).